BCL2 (BCL2 apoptosis regulator)
Diseases named in the same sentence as BCL2 in open-access papers (continued):
Sharing a sentence is not in itself a finding about the gene and the disease.
cutaneous T-cell lymphoma (3 papers, 2018 to 2021). "For the histone deacetylase (HDAC) inhibitor Panobinostat several resistance mechanisms have been observed such as overexpression of the anti-apoptotic protein Bcl-2 in cutaneous T-cell lymphoma patients." (PMID 31063487, 2019).
cystic fibrosis (3 papers, 2013 to 2020). Autosomal recessive disorder caused by pathogenic variants in the CFTR gene (cystic fibrosis transmembrane conductance regulator), which encodes a chloride and bicarbonate channel expressed in epithelial cells, and follow the diagnosis criteria. "The histopathological analysis showed reductions in cystic fibrosis, atretic ovaries, increased expression of Bcl-2 and E- Cadherin and reduced Bax expression in the group that received Aspirin and DHEA." (PMID 31608617, 2020). "Following inflammatory responses to LPS or allergen exposure, Bcl-2 expression is upregulated in airway epithelial cells of animal models of mucous hypersecretion and in patients with cystic fibrosis, asthma, and chronic bronchitis." (PMID 29323189, 2018).
dermatitis (3 papers, 2019 to 2026). An inflammatory process affecting the skin. "In this prospective cohort study, we found that symptoms of dermatitis radiation, pain, pruritus and fatigue were associated with the expression level of some genes of the DNA-damage response pathway (FDXR, SESN1, XPC, ZMAT3, ATM, BCL2/BAX, and CDKN1A)." (PMID 31632918, 2019).
disc degeneration (3 papers, 2014 to 2023). "When TNF-α is present in excessive amounts, as is often the case in pathological conditions like disc degeneration, it can lead to an increase in Bax and a decrease in Bcl-2, tipping the balance toward apoptosis." (PMID 37790932, 2023). "In order to study whether EA triggered remodeling of annular ECM by inhibiting apoptosis, we made a further study about the expression of Bcl-2 protein kindred in disc degeneration." (PMID 25763091, 2015). "Finally, to seek for potential therapeutic targets for apoptosis in disc degeneration, we performed immunohistochemistry for antiapoptotic Bcl-2 and SIRT1." (PMID 24472667, 2014). "Thus, the consistently decreased Bcl-2 and SIRT1 expression may contribute to the acceleration of apoptotic cell death in static compression-induced disc degeneration." (PMID 24472667, 2014).
Duchenne muscular dystrophy (3 papers, 2011 to 2020). Duchenne muscular dystrophy (DMD) is a neuromuscular disease characterized by rapidly progressive muscle weakness and wasting due to degeneration of skeletal, smooth and cardiac muscle. "In line with this, we earlier reported a constitutional expression of Bcl-2, a major anti-apoptotic protein, in muscle from healthy controls, but lower Bcl-2 expression in PM and Duchenne muscular dystrophy." (PMID 32936839, 2020). "Our new findings indicate that some genes repressed or activated by this mechanism (Bax, Bim, PUMA and Bcl2) may be important for protecting the muscle fiber against apoptosis, which may take place once the described mechanism is disrupted as occurs in a mouse model for Duchenne muscular dystrophy." (PMID 24282497, 2013). "Overexpression of Bcl-2 had no major effect in dystrophin-deficient mice, indicating that Bcl-2-mediated apoptosis is a more significant contributor to the pathogenesis of MDC1A than that of Duchenne muscular dystrophy." (PMID 21798088, 2011).
end-stage renal disease (3 papers, 2022 to 2025). "In unilateral ureteral obstruction (UUO), Bcl-2 levels are diminished and the same is seen in patients with end-stage renal disease (ESRD) who undergo dialysis." (PMID 39596166, 2024). "The results of the present study substantiated Bcl2's anti-apoptotic involvement in chronic renal disease in cats." (PMID 36699321, 2022). "Mean ± standard deviations (SDs) of other parameters and relative Bcl-2 abundance between clinically normal age-matched and chronic kidney disease cats." (PMID 36699321, 2022). "Bcl-2 levels of patients with end-stage renal disease, who were maintained on hemodialysis, underwent decreased expression when compared to the CKD group." (PMID 36699321, 2022). "However, there are few studies on the TGF-β1 signaling pathway, which involves MAPKs and Bcl-2, in cats with chronic kidney disease." (PMID 39858257, 2025). "This study revealed that Bcl-2 could help with distinguishing between cats with chronic kidney disease and healthy cats." (PMID 36699321, 2022). "Additionally, a prior investigation on human patients found that Bcl-2 levels were lower in patients with end-stage renal disease patients than in individuals with chronic kidney disease." (PMID 36699321, 2022). "We hypothesized that doxorubicin-induced cytotoxicity in feline kidney cells and the kidney tissue of cats with chronic kidney disease (CKD) would lead to increased levels of TGF-β1 and MAPK and decreased levels of Bcl-2." (PMID 39858257, 2025).
endometrial adenocarcinoma (3 papers, 2017 to 2023). "BCL2 gene is known to be regulated by ETS152, and an over expression of ETS1 in human endometrial adenocarcinoma HEC-1-A cells can result in an increase in BCL2 protein expression." (PMID 28765546, 2017). "Other researchers found a decreased expression of BCL-2 in atypical hyperplasia and endometrial adenocarcinoma, highlighting the need for further research to understand the specific mechanisms and roles of BCL-2 in oncogenesis and potential therapeutic interventions." (PMID 36937462, 2023). "In contrast, mifepristone could inhibit cell growth and induce apoptosis in Ishikawa endometrial adenocarcinoma cells through caspase-3 activation and regulating apoptotic genes such as BCL2/BAX and FAS/FASLG." (PMID 35869506, 2022).
enteritis (3 papers, 2022 to 2025). Inflammation of the small intestine. "The activation of Nrf2 in this study promoted the functional recovery of the intestinal barrier by increasing the expression of Bcl-2 and reducing apoptosis of epithelial cell following LPS treatment, which might explain why RUS ameliorated TNBS-induced enteritis in WT mice." (PMID 35308175, 2022).
Epithelial dysplasia (3 papers, 2006 to 2024). "Of the 11 cases of severe dysplasia, 72.70% showed Grade 3 Bcl-2 expression, which is higher than mild and moderate epithelial dysplasia." (PMID 39252711, 2024). "Epithelial dysplasia has been reported to be triggered by increased BCL2 expression via TLR sensing and NFkB activation in the presence of microbial imbalance." (PMID 36555145, 2022). "Furthermore, Bcl-2 has the potential to serve as a prognostic indicator for the identification of malignant transformation in epithelial dysplasia." (PMID 39252711, 2024).
Erythema (3 papers, 2021 to 2025). Redness of the skin, caused by hyperemia of the capillaries in the lower layers of the skin. "BCL-2 exerted significant immunomodulatory effects by regulating immune cell activity, inflammatory cytokine expression, and mast cell responses, contributing to the alleviation of AD clinical signs, such as erythema and edema." (PMID 40871454, 2025).
Fibroadenoma (3 papers, 2010 to 2026). A benign tumor of the breast characterized by the presence of stromal and epithelial elements. "We observed that the staining of fibroadenoma was similar to cancer tissue in SGK1 staining, but it was also similar to normal tissue in Bcl-2 staining." (PMID 37370761, 2023).
fluorosis (3 papers, 2019 to 2024). "The Col1a1, Bcl2, Fgfr1, Mmp9, Mmp13, Bmp2, and Bmp7 genes are the key regulatory factors in fluorosis bone metabolism." (PMID 39125380, 2024). "To examine the effect of gastrodin on bone tissue apoptosis in fluorosis rats, we measured the expression of apoptotic gene proteins, including caspase‐3, caspase‐9, Bax and Bcl‐2." (PMID 33010109, 2020). "In conclusion, gastrodin may reduce the level of ROS, improve the trabecular microstructure of rats with fluorosis and alleviate the toxic effects of fluoride on bone tissue by regulating the expression of Bcl‐2, Bax, caspase‐3 and caspase‐9 proteins." (PMID 33010109, 2020).
goiter (3 papers, 2018 to 2025). Enlargement of the thyroid gland usually caused by lack of iodine in the diet, hyperthyroidism, or thyroid nodules. "If MCL-1 or BCL-2 is decreased in lymphocytes, they survive less and have less stimulating thyrocyte apoptosis, leading to a greater goiter volume." (PMID 30018638, 2018). "In relation to MCL-1 in GD, patients with the lowest expression of this marker in lymphocytes are those with the largest goiters; those using beta-blockers also had lower expression of MCL-1 and BCL-2 in lymphocytes." (PMID 30018638, 2018).
Hashimoto thyroiditis (3 papers, 2012 to 2021). An autoimmune disorder caused by the production of autoantibodies against thyroid tissue. "Tissue specimens from all study participants showed the presence of diffuse infiltrates of mononuclear cells localized between thyroid follicles; some of these cells stained positively for CD8 or Bcl-2, thus confirming the initial clinical diagnosis of Hashimoto's disease or lymphocytic thyroiditis." (PMID 22527947, 2012).
hemangioma (3 papers, 2018 to 2022). A benign vascular lesion characterized by the formation of capillary-sized or cavernous vascular channels. "A study by Mabeta and Pepper showed that murine hemangioma overexpressed Bcl-2 and that such expression was diminished following antiangiogenic treatment." (PMID 29652858, 2018).
Hypothermia (3 papers, 2010 to 2022). Reduced body temperature due to failed thermoregulation. "Hypothermia was associated with significantly (P < 0.05) less upregulation of mRNA expression (Bcl-2 1.2 ± 0.5-fold, Bax 1.2 ± 0.6-fold compared with sham control)." (PMID 20158893, 2010). "Hypothermia also reduced the secretion of cytochrome c into the cytoplasm and increased the expression of the anti-apoptotic protein Bcl-2." (PMID 35743480, 2022).
influenza (3 papers, 2009 to 2023). An acute viral infection of the respiratory tract, occurring in isolated cases, in epidemics, or in pandemics; it is caused by serologically different strains of viruses (influenzaviruses) designated A, B, and C, has a 3-day incubation period, and usually lasts for 3 to 10 days. "Here, we find that enhancing NFkB signaling in T cells once memory to influenza is established, increases pro-survival Bcl-2 and CD122 levels thus boosting lung CD8+ TRM maintenance." (PMID 37468506, 2023). "Although not observed in our current study, over-expression of a subset of targets including the B-cell CLL/lymphoma 2 (BCL2) allowed MDCK cells to survive influenza infection during discovery of host genes against influenza virus infection." (PMID 19788744, 2009).
intracerebral hemorrhage (3 papers, 2018 to 2023). A cerebrovascular disorder characterized by bleeding into one or both cerebral hemispheres including the basal ganglia and the cerebral cortex. "Dex suppressed the hippocampus apoptosis in intracerebral hemorrhage rat brain injury through regulated caspase-3 and Bcl-2 expression and ameliorated memory impairment." (PMID 29351316, 2018). "A recent study has clarified that overexpression of HSPA9 prevents inflammation in a rat model of intracerebral haemorrhage through inhibition of inflammatory cytokines such as TNF-α, IL-β, Bax, and increased Bcl-2 levels." (PMID 35258800, 2022).
intrahepatic cholangiocarcinoma (3 papers, 2021 to 2025). A carcinoma that arises from the intrahepatic bile duct epithelium in any site of the intrahepatic biliary tree. "In addition, Gem and SFN-mediated HDAC inhibition caused increased Bax expression and decreased Bcl-2 expression in intrahepatic cholangiocarcinoma HuCCT-1 and HuH28 cells." (PMID 40006525, 2025). "The antiapoptotic Bcl-2 protein is overexpressed in cancer cells, as demonstrated in the Intrahepatic cholangiocarcinoma (iCCA) model, in which the increase expression of BCL-2 and c-FLIP is associated with the reduction in apoptosis due to the lack of activation of the caspase cascade." (PMID 35890188, 2022).
laryngeal tumor (3 papers, 2005 to 2024). "Such a strategy is highly likely to be beneficial for bcl-2 positive advanced stage laryngeal tumours that are currently managed with combination surgery and radiotherapy or combined chemo-radiotherapy." (PMID 15928664, 2005). "The antiapoptotic members of the family, bcl-2 and bcl-XL, and the proapoptotic member bax are reportedly expressed in 15, 74 and 81%, respectively, of laryngeal biopsy samples from advanced laryngeal tumours." (PMID 15928664, 2005). "Postoperative immunohistochemistry (IHC) results of the laryngeal tumor were as follows: cluster of differentiation 20 (CD20) (partial +), CD79α (diffuse +), CD5 (−), CD10 (−), CyclinD1 (−), B-cell lymphoma 2 (Bcl-2) (+), Bcl-6 (−), and Epstein Barr encoding region (EBER) in situ hybridization (−)." (PMID 39290501, 2024). "Postoperative IHC results of the laryngeal tumor were as follows: CD20 (+), CD79a (+), CD3 (−), CD10 (−), Bcl-2 (+), CD5 (−), Cyclin D1 (−), and CD23 (−)." (PMID 39290501, 2024). "Next, we examined the expression of BCL-2, BCL-XL, and MCL-1 in TMAs comprising tissue obtained from 191 SCCHN patients at the time of surgery, from oral cavity, hypopharyngeal and laryngeal tumors." (PMID 31801952, 2019).
leprosy (3 papers, 2006 to 2018). Leprosy is a chronic infectious disease affecting primarily the skin and peripheral nervous system. "Taken together, concerning miRNA regulation, our data suggest an antiapoptotic profile for leprosy in general, driven by BCL2, MCL1, and CASP8." (PMID 29593724, 2018). "Expression of Fas ligand and apoptotic proteins is found in leprosy lesions and M. leprae has been shown to activate pro-apoptotic Bcl-2 genes, Bak and Bax." (PMID 16978419, 2006).
leukocytosis (3 papers, 2013 to 2023). "To assess BCL-2 as a marker of proliferative activity in AML subgroups, we compared the degree of leukocytosis, as well as the presence/absence of peripheral blasts, between the BCL-2− and BCL-2+ subgroups." (PMID 32992732, 2020).
liposarcoma (3 papers, 2017 to 2025). A usually painless malignant tumor that arises from adipose tissue. "MiR-143 inhibits proliferation, induces apoptosis and cytokinesis of dedifferentiated liposarcoma cells by lowering BCL2, TOP2A, PRC1 and PLK1 expression." (PMID 28036291, 2017).
liver cirrhosis (3 papers, 2015 to 2023). "For example, it is possible to improve the survival of dLSECs by regulating the apoptosis suppressor gene BCL‐2, and thus improve the efficacy of treatment for chronic diseases such as liver cirrhosis." (PMID 36494102, 2023). "As expected, apoptosis of enterocytes was increased during the development of liver cirrhosis via regulating Bax and Bcl-2, and external administration of IGF-1 reduced enterocytic apoptosis in liver cirrhotic rats through regulating Bax and Bcl-2." (PMID 26152281, 2015). "Furthermore, the results showed that Bcl-2 and Bax were involved in the process of liver cirrhosis." (PMID 32503634, 2020). "In summary, IDWE exhibited a significant effect against CCl4 induced liver cirrhosis, which may be probably due to the antioxidant effect, relieve the inflammation reaction, down-regulated protein expression of NF-κB p65 and Bax, up-regulated Bcl-2 protein expression." (PMID 32503634, 2020).
liver failure (3 papers, 2015 to 2021). A liver disease characterized by the liver losing or has lost all of its function. "The ratio of Bax/Bcl-2 in apoptosis plays a key role in liver failure." (PMID 26770978, 2015). "Moreover, we have suggested the activation of related signaling transduction could induce Bcl-2 expression and inhibit Bad, TNF-α and IL-1β expression, which could ameliorate the apoptosis and necrosis of hepatocytes to prevent the liver failure." (PMID 32483425, 2020).
lung neoplasm (3 papers, 1997 to 2021). A benign or malignant, primary or metastatic neoplasm involving the lungs. "For instance, lung neoplasms (D008175) were regulated by 23 targets such as iNOS, Bcl2 and PKC that have anti-inflammatory, pro-apoptotic effects in the TME." (PMID 33460401, 2021).
malignant peripheral nerve sheath tumor (3 papers, 2010 to 2024). Malignant peripheral nerve sheath tumor (MPNST) is a rare and often aggressive soft tissue sarcoma occurring in a wide range of anatomical sites. "While CD99 and Bcl-2 are a common feature of SFTs, we used other markers to exclude relevant differential diagnoses, like CD31 (e.g., vascularized malignancies like spindled-cell angiosarcoma), Cytokeratin MNF116 (e.g., epithelioid sarcoma), or S100 (e.g., malignant peripheral nerve sheath tumor)." (PMID 38392213, 2024).
malignant pleural mesothelioma (3 papers, 2014 to 2024). A malignant neoplasm that arises from mesothelial cells in the pleura and shows a diffuse growth pattern. "Bcl-2 was decreased in malignant pleural mesothelioma following TRD-treatment too." (PMID 25568670, 2014).
meningitis (3 papers, 2009 to 2024). A disorder characterized by acute inflammation of the meninges of the brain and/or spinal cord. "The persistence of the infiltrate in Bcl-2 transgenic mice following meningitis in vivo suggested that neutrophils were not taken up by macrophages, and this might result in reduced secretion of TGF-β (IL-10 is not detectable in this model)." (PMID 19478887, 2009).
myopia (3 papers, 2024 to 2025). "Our study revealed that RGC apoptosis in experimental myopia decreased Bcl-2, increased Bax and induced retinal Ca2+ outflow." (PMID 40610752, 2025). "Meanwhile, we also found that the level of the anti-apoptotic gene BCL-2 was up-regulated in the sclera in the LIM group after 2 weeks of myopia induction, whereas the pro-apoptotic gene BAD level was decreased." (PMID 40216914, 2025). "The proapoptotic proteins Bax, Caspase-3, and Caspase-8 were upregulated in the retinas of chicks undergoing form deprivation, whereas the antiapoptotic protein Bcl-2 was downregulated, indicating that retinal cell apoptosis may be an important mechanism in the development of myopia." (PMID 39160465, 2024). "In the present study, we noted that under mild stress (stress lasting for 2-week myopia induction), activated PI3K/AKT signaling pathway promotes the expression of p-AKT2 and BCL-2, which can inhibit apoptotic signaling and contribute to cell survival." (PMID 40216914, 2025). "Further, we investigated the changes of PIK3R3, AKT2 and TGF-β1, E-cadherin, COLI, BCL-2, BAD, MMP2, and TIMP2 in the sclera of myopic guinea pigs to explore their effects on the development of myopia after 2- and 4-week myopic induction." (PMID 40216914, 2025). "After myopia induction for 2 and 4 weeks, the expression of PIK3R3, AKT2, BAD, BCL-2, TGF-β1, E-cadherin, COLI, MMP2, and TIMP2 was detected by qPCR." (PMID 40216914, 2025).